SRL (sarcalumenin)
Synonyms: SAR
Tractability: Antibody: UniProt places it where antibodies can reach, with medium confidence; UniProt predicts a signal peptide or a membrane-spanning region.
Gene: Protein-coding gene on chromosome 16 (4,189,374 to 4,242,083, reverse strand). Ensembl gene ENSG00000185739.
Subcellular location: Sarcoplasmic reticulum lumen; Sarcoplasmic reticulum membrane
Gene Ontology:
Molecular function: GTP binding
Biological process: store-operated calcium entry
Cellular component: sarcoplasmic reticulum lumen; sarcoplasmic reticulum membrane
Genetic constraint (gnomAD): Loss-of-function variants: 22 observed, 37.85 expected, observed/expected ratio (o/e) 0.58, 90% interval 0.41 to 0.83. The upper end of that interval is the gene's LOEUF score, 0.83, which puts it in group 3 of 6, group 1 being the genes least tolerant of losing a copy. Missense variants: 565 observed, 612.02 expected, observed/expected ratio (o/e) 0.92, 90% interval 0.86 to 0.99. Synonymous variants: 264 observed, 243.41 expected, observed/expected ratio (o/e) 1.08, 90% interval 0.98 to 1.2.
Homologues: Orthologues: macaque SRL (99% identical), chimpanzee SRL (97% identical), guinea pig SRL (96% identical), rabbit SRL (96% identical), mouse Srl (96% identical), pig SRL (96% identical), rat Srl (95% identical), tropical clawed frog srl (87% identical), zebrafish srl (81% identical), zebrafish SRL (62% identical), Drosophila melanogaster CG9297 (42% identical). Paralogues in human: EHD3 (30% identical), EHD1 (29% identical), EHD2 (29% identical), EHD4 (27% identical), ITSN2 (15% identical), EPS15L1 (14% identical), ITSN1 (14% identical), EPS15 (13% identical), REPS1 (8% identical), REPS2 (7% identical).
Diseases named in the same sentence as SRL in open-access papers:
SRL is named in the same sentence as 16 diseases in open-access papers, as found by Europe PMC text mining. Sharing a sentence is not in itself a finding about the gene and the disease. The quoted sentences say what the papers report.
Duchenne muscular dystrophy (1 paper, 2024). Duchenne muscular dystrophy (DMD) is a neuromuscular disease characterized by rapidly progressive muscle weakness and wasting due to degeneration of skeletal, smooth and cardiac muscle. "In fact, several studies have highlighted alterations in various calcium signalling and handling molecules such as calsequestrin‐1, sarcalumenin, myozenin‐1, annexins or dystrophin in ageing and muscle diseases for example, Duchenne muscular dystrophy." (PMID 39009419, 2024).
glioma (1 paper, 2016). A benign or malignant brain and spinal cord tumor that arises from glial cells (astrocytes, oligodendrocytes, ependymal cells). "An increase in mean fluorescent intensity is due to the higher expression level of LRP in C6 glioma cells than BCEC, therefore which can easily be targeted by the SRL peptide (as a LRP ligand) present on the surface of nanoparticles." (PMID 28243262, 2016).
hepatoma (1 paper, 2014). "SRL exhibited anti-proliferative activity toward both hepatoma Hep G2 cells and leukemia L1210 cells, with an IC50 of 7 μM and 19 μM, respectively." (PMID 25460311, 2014).
myonecrosis (1 paper, 2013). "The calcium-handling proteins sarcalumenin and calsequestrin-1 were increased in control EOM compared with control DIA, reinforcing the view that constitutional properties of EOM are important for their protection against myonecrosis." (PMID 23823696, 2013).
infection (1 paper, 2025). The state of being infected such as from the introduction of a foreign agent such as serum, vaccine, antigenic substance or organism. "Mechanistic studies explained that SRL promotes the intensity of CD8+ central memory T cells and their antigen-specific response in the context of infection through increasing CD62L expression." (PMID 40568581, 2025).
SRL also shares sentences with these, for which no sentence is quoted: actinomycosis (1 paper); Arrhythmia (1); atrial fibrillation (1); catecholaminergic polymorphic ventricular tachycardia (1); Hypertension (1); inflammation (1); leukemia (1); long-QT syndrome (1); osteosarcoma (1); short QT syndrome (1); tumor (1).